KBTBD4 (kelch repeat and BTB domain containing 4)
Description:
Substrate-specific adapter of a BCR (BTB-CUL3-RBX1) E3 ubiquitin ligase complex which targets CoREST corepressor complex components RCOR1, KDM1A/LSD1 and HDAC2 for proteasomal degradation. RCOR1 is likely to be the primary target while degradation of KDM1A and HDAC2 is likely due to their association with RCOR1. Also targets RCOR3, MIER2 and MIER3 for proteasomal degradation as well as associated proteins ZNF217 and RREB1. Degradation is dependent on the presence of an ELM2 domain in the target proteins.
Synonyms: BKLHD4; FLJ10450; HSPC252
Tractability: Small molecule: a structure with a bound ligand is known. PROTAC: ubiquitination databases record sites on it; its protein half-life has been measured.
Gene: Protein-coding gene on chromosome 11 (47,572,197 to 47,578,976, reverse strand). Ensembl gene ENSG00000123444.
Subcellular location (Human Protein Atlas): Nucleoplasm; Cytosol; Vesicles
Gene Ontology:
Biological process: proteasome-mediated ubiquitin-dependent protein catabolic process
Cellular component: Cul3-RING ubiquitin ligase complex
Genetic constraint (gnomAD): Loss-of-function variants: 29 observed, 42.84 expected, observed/expected ratio (o/e) 0.68, 90% interval 0.5 to 0.92. The upper end of that interval is the gene's LOEUF score, 0.92, which puts it in group 3 of 6, group 1 being the genes least tolerant of losing a copy. Missense variants: 562 observed, 688.14 expected, observed/expected ratio (o/e) 0.82, 90% interval 0.76 to 0.88. Synonymous variants: 253 observed, 266.78 expected, observed/expected ratio (o/e) 0.95, 90% interval 0.86 to 1.05.
Homologues: Orthologues: pig KBTBD4 (99% identical), chimpanzee KBTBD4 (99% identical), rabbit KBTBD4 (98% identical), rat Kbtbd4 (97% identical), macaque KBTBD4 (97% identical), dog KBTBD4 (96% identical), guinea pig KBTBD4 (96% identical), mouse Kbtbd4 (96% identical), tropical clawed frog kbtbd4 (80% identical), zebrafish kbtbd4 (74% identical), Drosophila melanogaster lute (16% identical), Drosophila melanogaster CG17068 (13% identical), and 2 more. Paralogues in human: BTBD3 (18% identical), BTBD6 (18% identical), BTBD1 (16% identical), BTBD2 (16% identical), BTBD9 (13% identical), ABTB3 (11% identical), ABTB2 (10% identical), ABTB1 (9% identical), SPOP (8% identical), SPOPL (7% identical), KLHL11 (7% identical).
Diseases named in the same sentence as KBTBD4 in open-access papers:
KBTBD4 is named in the same sentence as 9 diseases in open-access papers, as found by Europe PMC text mining. Sharing a sentence is not in itself a finding about the gene and the disease. The quoted sentences say what the papers report.
medulloblastoma (6 papers, 2017 to 2025). A malignant, invasive embryonal neoplasm arising from the cerebellum. "Recurrent indel mutations in the Kelch domain of the KBTBD4 E3 ligase rewire epigenetic programs for stemness in medulloblastoma by recruiting LSD1-CoREST-HDAC1/2 complexes as neo-substrates for ubiquitination and degradation." (PMID 40175372, 2025). "We show that medulloblastoma-associated hotspot mutations in the Kelch domain of KBTBD4 promote the recruitment of CoREST as a neo-substrate for ubiquitylation and degradation." (PMID 35379950, 2022). "We find that oncogenic mutations in the ubiquitin ligase KBTBD4 in group 3/4 medulloblastomas lead to the recruitment and ubiquitylation of epigenetic regulatory complexes containing CoRESTs and LSD1." (PMID 35379950, 2022). "The discovery of neomorphic mutations in KBTBD4 extends the spectrum of neomorphic mutations in cancer, highlighting KBTBD4 and the CoREST complex for further investigations of the origins and therapeutic opportunities in group 3/4 medulloblastomas." (PMID 35379950, 2022). "Therefore, we hypothesised that CoREST degradation induced by KBTBD4 mutations could result in increased stemness of medulloblastoma cells, as described in other tumour types." (PMID 35379950, 2022). "Second, we demonstrate that HDAC1/2 inhibitors can block the mutant KBTBD4–HDAC1 interface and proliferation of KBTBD4-mutant medulloblastoma cells." (PMID 39939763, 2025). "Identified in a phenotypic screen for hematopoietic stem-cell expansion, UM171 was later shown to converge mechanistically with pathogenic Kelch repeat and BTB domain-containing protein 4 (KBTBD4) insertions in medulloblastoma." (PMID 41452132, 2025). "Recent analyses also reveal recurrent in-frame insertions in KBTBD4 in 40% of cases of adult group 3 medulloblastomas." (PMID 35379950, 2022). "Recent analyses have revealed recurrent in-frame insertions in the E3 ubiquitin ligase adaptor Kelch Repeat and BTB Domain Containing 4 (KBTBD4) in cases of group 3/4 medulloblastoma." (PMID 35379950, 2022). "We further show that mutant KBTBD4 activates the transcription of CoREST targets favouring stemness, known to promote tumorigenesis in medulloblastoma." (PMID 35379950, 2022). "While DAOY cells are the most cited medulloblastoma cell-based model, they do not represent the non-WNT/non-SHH medulloblastoma classes in which the KBTBD4 mutations are detected." (PMID 35379950, 2022). "Cells expressing mutant KBTBD4 showed a reduction in CoREST protein level, whereas these levels were unchanged by expression of KBTBD4WT, consistent with data from other medulloblastoma cell lines." (PMID 35379950, 2022). "Medulloblastoma cell lines derived in the past 4 decades (n > 40), collectively show a surprising lack of genetic diversity and medulloblastoma cell lines containing mutant KBTBD4 have not been reported to date." (PMID 35379950, 2022). "Recurrent heterozygous in-frame insertion mutations in the Cullin RING ubiquitin Ligase 3 (CRL3) adaptor KBTBD4 are reported in children with non-WNT/non-SHH medulloblastoma, as well as in children and adults with Pineal Parenchymal Tumours of Intermediate Differentiation (PPTID)." (PMID 35379950, 2022). "However, our data obtained with 4 different models of medulloblastoma and HEK293T cells did not confirm binding of CoREST to KBTBD4WT, nor its ubiquitylation, suggesting a neomorphic effect in medulloblastoma cells resulting from KBTBD4 mutation." (PMID 35379950, 2022).
pineocytoma (3 papers, 2023 to 2025). "Whereas the pineocytomas showed no pathogenic variants in NGS panel sequencing except for a heterozygous PALB2 variant in a single case, hotspot KBTBD4 inframe insertions were found in all 4 PPTID-B samples and 9 of 11 PPTID-A cases." (PMID 41291966, 2025). "Whereas pineocytomas are benign pineal tumors with favorable survival but no known oncogenic driver alteration, PPTID (CNS WHO grade 2–3) show frequent inframe insertions in the KBTBD4 gene as the main oncogenic driver." (PMID 41291966, 2025).
tumor (6 papers, 2020 to 2025). "In PPTID KBTBD4 mutations as tumor initiating event were found, but KBTBD4-wildtype tumors were also identified." (PMID 41291966, 2025). "Delineating the role of KBTBD4 mutations thus offers significant opportunities to understand tumour pathogenesis and to exploit the underpinning mechanisms therapeutically." (PMID 35379950, 2022). "Critically, group 3/4 tumours with KBTBD4 mutations typically lack other gene-specific alterations, such as MYC amplification, indicating KBTBD4 insertion mutations as the primary genetic driver." (PMID 35379950, 2022). "As hypothesised, all KBTBD4 mutated primary tumours in the cohort (n = 3) resided in cluster 2 and demonstrated upregulation of KBTBD4 mutation-associated genesets." (PMID 35379950, 2022). "Cluster 2 represents 60% (134/223) of all MBGroup3/4 tumours examined, indicating a wider involvement of KBTBD4 mutation-associated transcriptional programmes and CoREST pathways in this tumour group, with KBTBD4-mutated cases representing a subset (3/134) of these cases." (PMID 35379950, 2022). "The first cluster displayed gene-set expression signatures similar to the KBTBD4WT models, while signatures of the second tumour cluster were similar to those of the KBTBD4 mutant models." (PMID 35379950, 2022). "Overall, our findings establish a potential mechanism of tumorigenesis through increased stemness in KBTBD4 mutant tumours." (PMID 35379950, 2022). "Our results suggest that HDAC1/2-selective inhibitors, such as RBC1HI, could selectively block the proliferation of KBTBD4-mutant MB tumour cells." (PMID 39939763, 2025). "We argue that these tumor types may benefit from a KBTBD4-activating/CoREST complex degrader therapy, which could also enhance antitumor immunity and sensitize resistant tumors to immunotherapy." (PMID 40479062, 2025). "Moreover, these expression signatures define a cluster of tumours which include, but extend beyond, KBTBD4 mutant cases to characterise a wider disease group." (PMID 35379950, 2022). "Using single sample Gene Set Enirchment Analysis (ssGSEA) of 223 primary MBGroup3/4 tumours, interrogation of KBTBD4 mutation-associated gene signatures identified in our models (including CoREST and ESC-related pathways) distinguished two clusters within these primary tumours." (PMID 35379950, 2022). "To determine the essentiality of KBTBD4, we used base editing in patient-derived xenograft (PDX) models derived from group 3 MB tumour specimens harbouring either KBTBD4-PR or wild-type KBTBD4 (KBTBD4-WT)." (PMID 39939763, 2025). "Adult Group 3 tumours lacked hallmark MYC amplifications, but had recurrent mutations in KBTBD4 and NOTCH1." (PMID 33172502, 2020). "Additional work is needed to determine whether SCLC-P tumor subtypes, which express the highest levels of MYC across all SCLC subtypes, would benefit from KBTBD4 activation through UM171, which not only degrades CoREST complex proteins but also suppresses MYC expression." (PMID 40479062, 2025).
cancer (5 papers, 2017 to 2025). A tumor composed of atypical neoplastic, often pleomorphic cells that invade other tissues. "Cancer mutations in KBTBD4, a CULLIN3-RING E3 ligase (CRL3) substrate receptor, present the first compelling case of E3 ligase neomorphic mutations." (PMID 39939763, 2025). "Using deep mutational scanning, we chart the mutational landscape of the KBTBD4 cancer hotspot, revealing distinct preferences by which insertions and substitutions can promote gain-of-function and the critical residues involved in the hotspot interaction." (PMID 39939763, 2025). "LSD1-CoREST-HDAC1/2 complexes are degraded by both the drug UM171 and cancer-associated mutations in the E3 ligase KBTBD4." (PMID 40175372, 2025). "In agreement, the KBTBD4 Kelch domain harbours the cancer hotspot mutations that confer neo-substrate interaction." (PMID 40175372, 2025). "In conjunction with a companion study, here we reveal a striking mechanistic mimicry between UM171 and the KBTBD4 cancer mutations." (PMID 39939763, 2025). "Here, we show a novel mechanism in cancer pathogenesis whereby indel mutations in KBTBD4 drive its recognition of neo-substrates for degradation." (PMID 35379950, 2022). "The degradation of CoREST promoted by KBTBD4 mutation diverts epigenetic programmes inducing significant alterations in transcription to promote increased stemness of cancer cells." (PMID 35379950, 2022). "We show that gain-of-function cancer mutations in the KBTBD4 E3 ligase promote neodegradation of substrates via a shape-complementarity-based mechanism, which converges with the mechanism of action of the UM171 molecular glue degrader and can be blocked by HDAC1/2 inhibitors." (PMID 39939763, 2025). "We found that UM171, a clinical phase 2 drug for haematopoietic stem cell transplantation, structurally mimics the cancer-mutated loop and acts as a molecular glue for wild-type KBTBD4 and HDAC1/2, resolving the long-standing puzzle of UM171’s mechanism of action." (PMID 40175372, 2025). "Given the known functions of PRKAG1-interacting proteins (e.g., BCDIN3D, KBTBD4, CUL3) in cell cycle regulation, we evaluated the association between PRKAG1 expression and cancer-related pathways using gene set variation analysis (GSVA)." (PMID 40958861, 2025). "Cryo-electron microscopy analysis of two distinct KBTBD4 cancer mutants bound to LSD1–HDAC1–CoREST reveals that a KBTBD4 homodimer asymmetrically engages HDAC1 with two KELCH-repeat β-propeller domains." (PMID 39939763, 2025). "The change of substrate specificity in KBTBD4 raises the intriguing possibility that neomorphic mutations could be present in other E3 ligases, which would further expand the variety of degrons participating in cancer development that have been identified through deep learning algorithms." (PMID 35379950, 2022). "Here we elucidate the mechanism by which hotspot cancer mutations in the E3 ligase KBTBD4 can reprogramme its PPIs to promote aberrant degradation of HDAC1/2 corepressor complexes in MB, establishing HDAC1/2 as the target of mutant KBTBD4." (PMID 39939763, 2025). "Structural analysis of KBTBD4-neo-substrate complexes was pursued to define how cancer mutations and UM171 could similarly co-opt KBTBD4 for neomorphic binding to CoREST1NT2-HDAC2." (PMID 40175372, 2025). "We identified several cancer-related pathways (PI3K, RAP1 and proteoglycans in cancer) significantly upregulated in cells expressing KBTBD4 mutants in accordance with pro-tumorigenic features." (PMID 35379950, 2022).
KBTBD4 also shares sentences with these, for which no sentence is quoted: childhood cancer (1 paper); CNS embryonal tumor (1); germ cell tumor (1); pineal parenchymal tumor (1); retinoblastoma (1).